ACOD1 (aconitate decarboxylase 1)
Diseases named in the same sentence as ACOD1 in open-access papers (continued):
Sharing a sentence is not in itself a finding about the gene and the disease.
atherosclerosis (4 papers, 2022 to 2025). A disease characterized by the build-up of fatty material and calcium deposition in the arterial wall resulting in partial or complete occlusion of the arterial lumen. "After confirmation that unmodified itaconate and Acod1 deficiency modulate macrophage inflammation, we investigated the role of Acod1-derived itaconate in a mouse model for atherosclerosis." (PMID 38309122, 2024). "As FCs are a specific subset of macrophages in atherosclerosis, we tested how Acod1 deficiency affects these cells." (PMID 38309122, 2024). "In our study, we found that Nrf2 levels increased with atherosclerosis, and that OI treatment enhanced this Nrf2 increase, whereas Acod1 deficiency caused Nrf2 levels to decrease." (PMID 38085578, 2023). "We found that multiple proinflammatory cytokines and chemokines were downregulated by OI treatment but upregulated by Acod1 deficiency during atherosclerosis, which is consistent with their effects on atherogenesis and with other studies." (PMID 38085578, 2023). "Loss of the enzyme that synthesizes itaconate, Acod1, promoted atherogenesis, whereas delivery of the itaconate derivative OI, which enhances the effect of itaconate, suppressed atherosclerosis in WT mice." (PMID 38085578, 2023). "Interestingly, the new in vivo data we present here rather shows that Acod1 deficiency is beneficial in atherosclerosis, as highlighted by the decreased necrotic core size." (PMID 38309122, 2024). "RNA-seq and single-cell RNA-seq (scRNA-seq) data revealed low ACOD1 expression in human carotid plaques, in contrast with established atherosclerosis markers." (PMID 40504626, 2025). "Clearly our studies warrant future research into the potential use of the ACOD1-itaconate axis to manage atherosclerosis progression." (PMID 38309122, 2024). "Based on the data provided in our study, we propose that silencing the Acod1-itaconate axis in atherosclerosis leads to a favourable plaque phenotype." (PMID 38309122, 2024). "Yet, it should be noted that another recent publication that employs an alternate way of atherosclerosis induction rather shows that Acod1 knockout elicits increased inflammation and larger plaques." (PMID 38309122, 2024). "Our results indicate that myeloid-specific expression of Acod1 protects mice from atherosclerosis, as Acod1fl/flLysMcre mice demonstrated aggravated atherogenesis compared with the Acod1fl/fl control." (PMID 38085578, 2023). "Deletion of Acod1 in myeloid cells exacerbated inflammation and atherosclerosis in vivo and resulted in an elevated frequency of a specific subset of M1-polarized proinflammatory macrophages in the atherosclerotic aorta." (PMID 38085578, 2023). "The relevance of ACOD1 in human atherosclerosis warrants further studies." (PMID 40504626, 2025). "Since targeting the Acod1-itaconate axis could be a promising modulator of atherosclerosis progression, we first reassessed itaconate's immunomodulatory properties." (PMID 38309122, 2024). "In this paper, we explore Acod1 as a modulator of atherosclerosis progression." (PMID 38309122, 2024). "In the current study, we investigate the immunomodulatory properties of itaconate, an immunometabolite derived from the TCA cycle intermediate cis-aconitate and synthesised by the enzyme Aconitate Decarboxylase 1 (ACOD1, also known as IRG1), in the context of atherosclerosis." (PMID 38309122, 2024).
atherosclerosis (continued). "Importantly, CD8+ T cells displayed an increased frequency among T lymphocytes from Acod1–/– aortic plaques compared with WT, consistent with their role in promoting atherosclerosis." (PMID 38085578, 2023). "Notably, levels of peripheral neutrophils and monocytes were initially similar in Acod1–/– and WT mice, but both were increased in Acod1–/– mice compared with WT after 8 to 10 weeks of hypercholesterolemia, coincident with atherosclerosis." (PMID 38085578, 2023). "Collectively, these results suggest that hypercholesterolemia and atherosclerosis lead to increased levels of Acod1 and itaconate, which in turn may help to attenuate atherogenesis." (PMID 38085578, 2023). "Based on our own and others’ in vitro data showing increased inflammatory responses in the absence of Acod1 in macrophages, one might expect a worse atherosclerosis outcome in Acod1-deficient mice." (PMID 38309122, 2024). "Additionally, compared with atherosclerotic WT mice, atherosclerotic Acod1–/– mice exhibited a more than 3-fold increase in necrotic area in the aortic root, a surrogate of plaque instability in the murine model of atherosclerosis." (PMID 38085578, 2023). "Thus, the absence of Acod1 during the development of atherosclerosis is associated with elevated levels of circulating neutrophils and monocytes." (PMID 38085578, 2023). "A recent paper indeed shows that atherosclerosis induction by PCSK9-AAV administration results in increased inflammation and lesion area in mice that lack ACOD1, and the authors propose an important role of NRF2 in mediating this phenotype." (PMID 38309122, 2024). "Therefore, based on this data and previous research performed on the role of Ly6Clow monocytes in plaques, increased circulating Ly6Clow monocytes when targeting Acod1 in atherosclerosis is not detrimental to disease progression." (PMID 38309122, 2024). "To determine whether itaconate biosynthesis changes during atherogenesis, we examined the expression of Acod1 in mice with or without atherosclerosis." (PMID 38085578, 2023).
Cerebral ischemia (4 papers, 2022 to 2025). Restriction of arterial blood supply to the brain associated with insufficient oxygenation to support the metabolic requirements of the tissue. "It was recently reported that in a MCAO model, the endogenous ACOD1 was protective against cerebral ischemia/reperfusion injury." (PMID 39060766, 2024). "Using MCAO and in vitro ischemia models, we showed that LINC00894 stabilized EIF5 to enhance the expression of ATF4, which transcriptionally regulated the expression of FGF21 and ACOD1, thus protecting cells from brain ischemia-induced damage." (PMID 39060766, 2024). "More recently, a study demonstrated that Acod1 KO mice presented significant increase in cerebral lesion volume compared to control mice and illustrated that ACOD1 suppressed cerebral ischemia-reperfusion injury by oxidative stress regulation." (PMID 35677353, 2022). "Additionally, Acod1 has an inhibitory role in mouse cerebral ischemia-reperfusion injury." (PMID 38730297, 2024). "Our results demonstrated that LINC00894 regulated cerebral ischemia injury by stabilizing EIF5 and facilitating EIF5-ATF4-dependent induction of FGF21 and ACOD1." (PMID 39060766, 2024).
endotoxemia (4 papers, 2022 to 2024). "ACOD1/itaconate deficiency has also been shown to exacerbate endotoxemia-induced acute lung injury via the inhibition of autophagy." (PMID 39351225, 2024). "Intriguingly, in an LPS-induced endotoxemia model, induction of ACOD1 was found to reduce TNF production, which also deviates from our findings in an inhaled exposure model." (PMID 39351225, 2024). "Growing evidence points towards an instrumental role of ACOD1 and itaconate in promoting bacterial replication, sustaining pro-inflammatory cytokine production, and lethal innate immune responses in mouse models of experimental endotoxemia and microbial sepsis." (PMID 38302438, 2024).
gout (4 papers, 2020 to 2023). A condition characterized by painful swelling of the joints, which is caused by deposition of urate crystals. "RNA sequencing, bio-informatics analysis, RT-PCR, and Western blot demonstrated that Sirt3 could suppress the expression of Acod1 (Irg1), which plays an important role in gout." (PMID 37468929, 2023).
injury (4 papers, 2022 to 2025). Damage inflicted on the body as the direct or indirect result of an external force, with or without disruption of structural continuity. "For example, the expression of Acod1 is increased in subjects with ischemia–reperfusion liver injury, and the importance of the Acod1-itaconate axis as well as the therapeutic efficacy of 4-OI have been revealed using Acod1-deficient mice." (PMID 35457208, 2022).
ischemia (4 papers, 2021 to 2025). A hypoperfusion of the BLOOD through an organ or tissue caused by a PATHOLOGIC CONSTRICTION or obstruction of its BLOOD VESSELS, or an absence of BLOOD CIRCULATION. "On the other hand, it is different from the result that the necrotic area caused by hepatic ischemia–reperfusion (I/R) in ACOD1-deficient mice was completely inhibited by 4-OI treatment." (PMID 35457208, 2022). "Based on these findings, we believed that AAV-mediated ectopic expression of LICN00894 could affect FGF21 and ACOD1 expression, through which the protective effect against ischemia-induced brain injury is exercised." (PMID 39060766, 2024). "Aconitate decarboxylase 1 (ACOD1, also known as IRG1) produces itaconate, a TCA cycle metabolite recently recognized for its role in modulating the TCA cycle and inflammatory responses in ischemia." (PMID 40536592, 2025).
pancreatic cancer (4 papers, 2023 to 2025). "Our study provides a proof of concept that ACOD1 is a potential target for immune-oncology drugs and IRG1-deficient macrophages represent a potent cell therapy strategy for cancer treatment even in pancreatic tumors that are resistant to T cell–based immunotherapy." (PMID 37115931, 2023). "In line with the in vitro results, in vivo assay using a pancreatic tumor mouse model with IP injected AsPC-1 cells also demonstrated the stronger anti-tumor activity of ACOD1-/- MSLN-CAR-iMACs." (PMID 37723178, 2023). "The M1 markers were significantly elevated in ACOD1-/- MSLN-CAR-iMACs compared with unmodified MSLN-CAR-iMACs after co-cultured with AsPC-1 pancreatic cancer cells for 24 h." (PMID 37723178, 2023). "In ovarian or pancreatic cancer mouse models, ACOD1-depleted CAR-iMACs exhibit enhanced capacity in repressing tumors, leading to increased survival." (PMID 37723178, 2023).
ischemic stroke (3 papers, 2021 to 2025). A stroke disorder caused by obstruction of blood flow to the brain, due to thrombotic (local blood clot formation) or embolic (due to a blood clot or other material traveling from another site) event. "Previous research suggested that ischemic stroke or LPS stimuli increased ACOD1." (PMID 40536592, 2025).
Stroke (3 papers, 2021 to 2025). Sudden impairment of blood flow to a part of the brain due to occlusion or rupture of an artery to the brain. "Interestingly, Acod1 deletion in a mouse model of stroke aggravates BBB disruption, and the treatment with dimethyl itaconate alleviates BBB disruption in mouse models of stroke mice and autoimmune encephalomyelitis." (PMID 40761766, 2025).
ulcerative colitis (3 papers, 2022 to 2024). An inflammatory bowel disease involving the mucosal surface of the large intestine and rectum. "However, the association between the Acod1 (Aconitate decarboxylase 1)-itaconate axis and ulcerative colitis has rarely been studied." (PMID 35457208, 2022). "ACOD1 exhibits abnormal expression in ulcerative colitis (UC)." (PMID 36770726, 2023).
acute kidney injury (2 papers, 2024 to 2025). Sudden and sustained deterioration of the kidney function characterized by decreased glomerular filtration rate, increased serum creatinine or oliguria. "Acod1/Itaconate also protects renal cells from oxidative stress induced by ischemia-reperfusion injury and acute kidney injury by promoting the Nrf2 pathway." (PMID 38730297, 2024).
asthma (2 papers, 2022 to 2026). "Multi-omics and single-cell sequencing analysis found that aconitate decarboxylase 1 (ACOD1)/ITA was significantly elevated in neutrophils via the NF-κB signaling pathway in DEP-exacerbated asthma." (PMID 41800242, 2026). "Knockout of Acod1 exacerbated asthma pathogenesis, while treatment with exogenous ITA or 4-octyl itaconate (4-OI) conferred protection against airway inflammation and reversed corticosteroid resistance in asthma mouse models." (PMID 41800242, 2026).
cognitive deficits (2 papers, 2022 to 2024). "Moreover, the protective effect of Acod1/itaconate axis in T. gondii-induced cognitive deficits was evaluated." (PMID 36618398, 2022). "Genes involved in the cognitive impairment MAG, GDF15, GPR176, and EPHB1 (upregulated), BCL11B, GIMAP7, and ACOD1 (downregulated) were differentially expressed." (PMID 38755198, 2024).
colorectal cancer (2 papers, 2024 to 2025). A primary or metastatic malignant neoplasm that affects the colon or rectum. "In colorectal cancer, macrophages serve as the main source of itaconate; knockout of ACOD1 in myeloid cells significantly suppresses the malignant proliferation of multiple tumors, including colorectal cancer." (PMID 41488637, 2025).
COVID-19 (2 papers, 2023 to 2024). A disease caused by infection with severe acute respiratory syndrome coronavirus 2. "Along with this idea, severely affected male COVID-19 patients carrying loss-of-function TLR7 variants exhibit decreased levels of ACOD1 mRNA." (PMID 38605883, 2024). "Of the DEGs that overlapped between healthy and COVID-19 PBMCs, 17 were upregulated, among which IL1R2, whereas the genes encoding for the cytokine tumor necrosis factor superfamily member 15 (TNFSF15) and ACOD1 were downregulated by dexamethasone." (PMID 37614228, 2023). "In addition, ex vivo dexamethasone treatment downregulated the ACOD1 gene in PBMCs derived from both healthy individuals and COVID-19 patients." (PMID 37614228, 2023).
Hepatic steatosis (2 papers, 2024). Steatosis is a term used to denote lipid accumulation within hepatocytes. "Overall, these data indicate that Acod1 deficiency protects mice from hepatic steatosis and the NAFLD-associated urea cycle dysfunction induced by fat overfeeding." (PMID 38302438, 2024). "Acod1 loss opposes glycemic homeostasis alterations, liver steatosis, and associated urea cycle dysfunction as well as dampens meta-inflammation signatures induced by overnutrition in mice." (PMID 38302438, 2024). "Histological examination of liver sections and quantitative determination of hepatic triglyceride content clearly showed that Acod1 loss attenuated HFD-induced liver steatosis." (PMID 38302438, 2024). "Given the aberrant steatosis observed in response to Acod1 deficiency in male mice, we next evaluated if inflammation drives the development of hepatic steatosis in a sex-dependent manner." (PMID 38305778, 2024). "In line with changes in liver weight, the transplant of Acod1-/- fecal microbiota in wild-type mice also decreased liver steatosis and increased hepatic mRNA levels of Nags, Cps1 and Ass1 urea cycle genes." (PMID 38302438, 2024). "Furthermore, by proteomics and analytical chemistry-integrated approaches we demonstrated that Acod1 ablation opposes the urea cycle dysfunction promoted by liver steatosis, known to play an instrumental role in the progression of NAFLD." (PMID 38302438, 2024). "In line with protection from diet-induced liver steatosis, functional enrichment analysis ranked urea cycle as the most significantly altered pathway by HFD regimen and rescued in Acod1-/- mice." (PMID 38302438, 2024). "Also, increased ACOD1 expression was found in livers of NAFLD patients in dependency of disease severity and hepatic steatosis grades." (PMID 38302438, 2024).
Insulin resistance (2 papers, 2023 to 2024). Increased resistance towards insulin, that is, diminished effectiveness of insulin in reducing blood glucose levels. "Importantly, oral administration of itaconate (1 mM) to HFD-fed Acod1-/- mice was sufficient to rescue the levels of itaconate accumulation in the colon and to restore the effects of gene loss on body weight gain, adiposity and insulin resistance." (PMID 38302438, 2024).
myocarditis (2 papers, 2023 to 2025). Myocarditis is a condition that is characterized by inflammation of the heart muscle (myocardium). "RNA-seq analysis identified Spp1, Lipg, and Acod1 among the most significantly and consistently upregulated genes across all myocarditis models, as defined by their high fold-change and statistical significance." (PMID 41222876, 2025). "Although WT infected mice did exhibit some inflammation in heart tissue, Acod1-/- mice had statistically significant increases in lesion severity compared to WT, exhibiting periarteritis, myocarditis and valvulitis." (PMID 38157387, 2023).
Q fever (2 papers, 2023 to 2024). A bacterial infection caused by Coxiella burnetii. "ACOD1-itaconate is essential for macrophage-mediated control of the intracellular pathogen Coxiella (C.)burnetii, which causes Q fever." (PMID 39156902, 2024). "Notably, the effect of deletion of Acod1 on C. burnetii replication was much stronger than the impact of deficiencies of several other IFNγ‐induced antimicrobial defense mechanisms (NOS2, IDO1/2, GBPs), thus establishing ACOD1 as a major protective determinant in the host defense against Q fever." (PMID 36479617, 2023). "Here, we identify the enzyme cis‐aconitate decarboxylase 1 (ACOD1 or IRG1) and its product itaconate as protective host immune pathway in Q fever." (PMID 36479617, 2023). "Thus, ACOD1‐derived itaconate is a key factor in the macrophage‐mediated defense against C. burnetii and may be exploited for novel therapeutic approaches in chronic Q fever." (PMID 36479617, 2023). "Here, we identify the ACOD1‐ITA axis as a key MyD88‐dependent macrophage‐autonomous determinant of early containment of C. burnetii and control of Q fever." (PMID 36479617, 2023).
staphylococcus aureus pneumonia (2 papers, 2025). An pneumonia caused by infection with Staphylococcus aureus. "In a Staphylococcus aureus pneumonia model, the interaction between aconitate decarboxylase 1 (ACOD1) and TLR4 exacerbates lung injury by activating NF-κB signaling." (PMID 41293166, 2025).
type 2 diabetes (2 papers, 2020 to 2024). "Although the roles of Serpina11, Cdh16, Lrrc27, and Lrrc66 in regulating islet function remain unclear, Acod1 is known to be important in modulating the immune system and mitochondrial function, and Fgf21 can protect against type 2 diabetes in mice by increasing insulin expression and secretion." (PMID 32527043, 2020).
airway hyperresponsiveness (1 paper, 2024). "We used Acod1-deficient (knockout) mice to characterize the relative changes in inflammatory responses, carbohydrate metabolism, pathology, tissue repair, and airway hyperresponsiveness (AHR) that occur in the absence of ACOD1." (PMID 39351225, 2024). "Furthermore, investigations into the functional significance of ACOD1 following LPS and ODE exposures demonstrated that ACOD1 mediates proinflammatory responses and airway hyperresponsiveness to environmentally relevant exposures." (PMID 39351225, 2024).
Anxiety (1 paper, 2026). Intense feelings of nervousness, tension, or panic often arise in response to interpersonal stresses. "Genetic knockout of Acod1 induced the anxiety-like phenotypes, which were rescued by DI administration." (PMID 41824475, 2026).
aphthous ulcers (1 paper, 2025). "However, ACOD1 mRNA was barely detectable in aphthous ulcers or inflamed mucosa (max 18 TPM)." (PMID 40386941, 2025).